SYK (spleen associated tyrosine kinase)
Diseases named in the same sentence as SYK in open-access papers (continued):
Sharing a sentence is not in itself a finding about the gene and the disease.
dermatitis (1 paper, 2017). An inflammatory process affecting the skin. "The B cell deficient and spleen tyrosine kinase (SYK) inhibitor-treated MRL/lpr mice were found not to develop spontaneous dermatitis and rituximab has been shown to have a therapeutic effect against cutaneous lesions in patients with SLE." (PMID 28950886, 2017).
endothelial dysfunction (1 paper, 2023). In vascular diseases, endothelial dysfunction is a systemic pathological state of the endothelium (the inner lining of blood vessels) and can be broadly defined as an imbalance between vasodilating and vasoconstricting substances produced by (or acting on) the endothelium. "Small molecule inhibitors like SYK inhibitors show promise in countering anti-spike-IgG-induced inflammation and endothelial dysfunction." (PMID 38187394, 2023).
escherichia coli infection (1 paper, 2013). Infection with the organism Escherichia Coli. "Two other SYK-related pathways, B cell receptor signaling pathway and the pathogenic Escherichia coli infection pathway, are discovered using combined datasets." (PMID 23941207, 2013).
esophageal cancer (1 paper, 2018). A primary or metastatic malignant neoplasm involving the esophagus. "Functional studies in esophageal cancer cell line showed siRNA mediated knock down of SYK inhibited proliferation, invasion/migration capability of cells." (PMID 29719615, 2018).
graft versus host disease (1 paper, 2018). An immune system disorder that occurs after allogeneic hematopoietic stem cell transplant and is a reaction of donor immune cells against host tissues. "In human patients with graft versus host disease (GVDH), total SYK levels were found to be higher than those in healthy patients." (PMID 29740433, 2018).
hepatitis (1 paper, 2022). Inflammation of the liver. "Recent studies indicated SYK regulates the alternative p38 activation, which could be the important mechanism in toxic substance-induced hepatitis." (PMID 36568669, 2022). "Especially, the activation of SYK in peripheral blood mononuclear cells and inflammatory macrophages is enhanced in patients with hepatitis, suggesting the potential of non-hepatic SYK as therapeutic target." (PMID 36568669, 2022).
hypogammaglobulinemia (1 paper, 2025). "Here, we describe a novel pathogenic, monoallelic variant in SYK in an adult presenting with hypogammaglobulinemia and atypical immune dysregulation." (PMID 41114848, 2025). "We identified a novel gain-of-function variant in SYK to underlie hypogammaglobulinemia and atypical autoinflammatory disease." (PMID 41114848, 2025).
lentivirus infection (1 paper, 2018). Virus diseases caused by the Lentivirus genus. "Taken together, these results demonstrated that the SYK gene was successfully expressed in DCs by lentivirus infection and that SYK-DCs generated in vitro could stimulate naïve T cells to become active and express higher levels of CD3+CD8+, TCRαβ+, CD3+CD38+, and CD3+HLA-DR+ compared with controls." (PMID 29372378, 2018).
mucous membrane pemphigoid (1 paper, 2025). Mucous membrane pemphigoid is a bullous dermatosis characterized clinically by blistering of the mucous membranes followed by scarring, and immunologically by IgG, IgA and/or C3 deposits on the epidermal basement membrane. "Attenuated disease progression was observed only in models where PI3Kδ was integrated into the kinome activation network, particularly those dominated by cGMP-/cAMP-dependent protein kinases (immunization-induced EBA) as well as the SYK/Src kinases (mucous membrane pemphigoid)." (PMID 41301467, 2025).
non-alcoholic steatohepatitis (1 paper, 2022). "On the other side, the positive correlation also can be found between SYK expression and the pathogenesis of non-alcoholic steatohepatitis (NASH), and the administration of SYK inhibitor (R406) with PLGA nanoparticles is regarded as a potential therapeutic approach against mouse NASH." (PMID 36568669, 2022).
occlusive vascular disease (1 paper, 2013). "The use of inhibitors of SYK is a potential treatment for occlusive vascular disease, due to its effect in modulating platelet aggregation and thrombus formation." (PMID 23874591, 2013).
oral cancer (1 paper, 2017). "Collectively, VEGF, PCNA and MMP9 may modulate the proliferation, migration, and invasion of oral cancer cells under the regulation of SYK." (PMID 29137391, 2017). "Piceatannol, a selective SYK inhibitor, similar to SYK knockdown, suppressed these malignant phenotypes on SYK-positive CAL27 cells, suggesting the significant role of SYK on oral cancer progression." (PMID 29137391, 2017).
osteonecrosis (1 paper, 2021). A none disease characterized by death of bone tissue due to a lack of blood supply. "In the Steroid-induced osteonecrosis of the femoral head-bone marrow mesenchymal stem cells, five circRNA targeted mRNAs including CLASP1, ENOX2, SYK, UBE2G2, and WNT5B were up-regulated by circRNA42." (PMID 34753940, 2021).
ovarian tumours (1 paper, 2004). "DNA hypermethylation in SYK gene has been found in 16.3% ovarian tumours (7 out of 43)." (PMID 14970867, 2004).
pancreatic adenocarcinoma (1 paper, 2018). "SYK acts as a tumor suppressor in pancreatic adenocarcinoma and regulates cellular growth and invasion." (PMID 29719615, 2018).
pancreatic ductal adenocarcinoma (1 paper, 2021). An infiltrating adenocarcinoma that arises from the epithelial cells of the pancreas. "The SYK gene is a potential marker and tumor suppressor for the reduced expression of human BC and pancreatic ductal adenocarcinoma (PDAC)." (PMID 34575665, 2021).
pneumonia (1 paper, 2022). An acute, acute and chronic, or chronic inflammation focally or diffusely affecting the lung parenchyma, caused by an infection in one or both of the lungs (by bacteria, viruses, fungi, or mycoplasma.). "Compared with the model group, isorhamnetin reduced the protein expressions of SYK, IL-6, MAPK14, MAPK8, TNF-α, AKT, p-Akt, PIK3CA, EGFR and IL-1β in lung tissues of pneumonia mice." (PMID 36506534, 2022).
rash (1 paper, 2025). "Meta-analysis from 4 publications (n = 574 patients) showed higher overall incidence of rash in adult ITP patients who received SYK and/or BTK inhibitors when compared to those who received placebo (RR 2.39; 95%CI: 1.01 – 5.70, p=0.05, I2 = 0%, random-effect model)." (PMID 41458387, 2025).
renal carcinoma (1 paper, 2018). A carcinoma arising from the epithelium of the renal parenchyma or the renal pelvis. "Silencing of the SYK long isoform by two independent specific siRNAs substantially reduced proliferation of renal cancer cells in 786-O and A498 cell lines as measured by colony-formation and viability assays." (PMID 29861861, 2018). "These include spleen tyrosine kinase (SYK), which we further validate as a key proliferation regulatory factor in renal cancer cells." (PMID 29861861, 2018). "Therefore, we used RNAi to examine whether modulation of long isoform of SYK influences the proliferation of renal cancer cells." (PMID 29861861, 2018). "This is exemplified by the identification of SYK in renal cancer; while AbHAC predicted SYK as a novel relevant factor, SYK had not been identified as an up-regulated gene in ccRCCs." (PMID 29861861, 2018).
renal fibrosis (1 paper, 2022). A final common manifestation of a wide variety of chronic kidney diseases characterized by glomerulosclerosis and tubulointerstitial fibrosis. "Moreover, has-mir-136-5p can improve renal fibrosis by targeting SYK and inhibition of TGF-β1/Smad3 signaling pathway." (PMID 35755170, 2022).
respiratory allergies (1 paper, 2019). "In respiratory allergies, SYK is known to be up-regulated and inhibitors have been used as therapies." (PMID 31531378, 2019).
Robinow syndrome (1 paper, 2011). Robinow syndrome (RS) is a rare genetic syndrome characterized by limb shortening and abnormalities of the head, face and external genitalia. "The deletion does not involve the PTCH1 gene, but instead 30 other gene,s including the ROR2 gene (MIM *602337) which causing both brachydactyly type 1 (MIM #113000) and Robinow syndrome (MIM #268310), and the immunologically active SYK gene (MIM *600085)." (PMID 21693067, 2011).
Shock (1 paper, 2024). The state in which profound and widespread reduction of effective tissue perfusion leads first to reversible, and then if prolonged, to irreversible cellular injury. "We re-analyzed the clinical dataset for SYK gene expression, and the result showed that, when compared to healthy volunteers, SYK gene expression was significantly increased in patients diagnosed with septic shock 24h after surgery (P<0.05) compared to the healthy control group." (PMID 39559354, 2024).
systemic mastocytosis (1 paper, 2017). Systemic mastocytosis (SM) comprises a heterogeneous group of rare acquired and chronic hematological malignancies that are related to an abnormal proliferation of mast cells in tissue, including bone marrow, with or without skin involvement. "Midostaurin and its metabolites, CGP52421 and CGP62221, have been reported as inhibitors of SYK in advanced systemic mastocytosis." (PMID 28881711, 2017). "SYK has previously been shown to be a target of midostaurin and its metabolites, CGP52421 and CGP62221, in advanced systemic mastocytosis, a hematopoietic neoplasm characterized by expansion and abnormal accumulation of mast cells." (PMID 28881711, 2017).
testicular germ cell tumor (1 paper, 2025). A germ cell tumor arising from the testis. "In testicular germ cell tumors (TGCT), UBD expression was significantly positively correlated with SYK, PI3K p85, IRF1, PKC-panbeta II (phosphorylated at S660), and STAT5α." (PMID 41347086, 2025).
triple-negative breast carcinoma (1 paper, 2018). An invasive breast carcinoma which is negative for expression of estrogen receptor (ER), progesterone receptor (PR), and human epidermal growth factor receptor 2 (HER2). "SYK has been suggested as a potential druggable target for a subset of triple negative breast cancers." (PMID 29719615, 2018).
uveitis (1 paper, 2018). An inflammatory process affecting a part of or the entire uvea. "For its specific contribution on the pathogenesis of uveitis, SYK/CARD9 signaling axis participates in the pathogenesis of autoimmune eye diseases, including ocular inflammatory disorders, uveitis, and dry eye disease." (PMID 30349554, 2018).
vitiligo (1 paper, 2023). Generalized well circumscribed patches of leukoderma that are generally distributed over symmetric body locations and is due to autoimmune destruction of melanocytes. "Cerdulatinib, a dual SYK/JAK kinase inhibitor, has been evaluated for its safety and tolerability in the treatment of vitiligo in topical training (0.37% cerudulatinib gel BID)." (PMID 36902341, 2023).
vulvovaginal candidiasis (1 paper, 2023). Infection of the vulva and vagina with a fungus of the genus CANDIDA. "STRING analysis demonstrated that SYK, TLR4, CARD9, and TLR2 are involved in vulvovaginal candidiasis and infectious disease pathways." (PMID 37238269, 2023).
tumor (155 papers, 2004 to 2026). "In particular, engagement of BTN2A1 expressed on M2-polarized macrophages and tumor-associated macrophages (TAMs) via a specific antibody promotes their reprogramming into M1-polarized macrophages through the SYK and MAPK signaling pathways." (PMID 41596393, 2026). "It interacts with tumor cells in an α-2,3-linked sialic acid-dependent manner, activates the SYK phosphorylation pathway, promotes immunosuppressive cytokine secretion, accelerates tumor growth, and impairs CD8+ T cell function." (PMID 41158758, 2026). "Although we found that SYK is associated with a malignant phenotype and contributes to shaping the immunosuppressive tumor microenvironment in diffuse glioma, this study still has the following limitations." (PMID 35910221, 2022). "Consistent with the immune checkpoints, the mRNA levels of SYK were positively associated with tumor mutation burden (TMB) in multiple tumors, including GBM and MESO (p < 0.05)." (PMID 35910221, 2022). "SYK expression was also significantly associated with tumor stage and location, but significance was dependent on the type of variant analyzed." (PMID 28957395, 2017). "Beside the biological differences associated with these tumor characteristics, we showed that expression of SYK(T) and its splice variants was significantly different for left- vs right-sided tumors and for MSS vs MSI tumors in the MATCH cohort." (PMID 28957395, 2017). "Overall, the findings in literature and the current study suggest that SYK(S) is associated with tumor promoting activities while SYK(L) is associated with tumor suppressing activities." (PMID 28957395, 2017). "In aggregate, the long isoform SYK(L) appears to be associated with tumor suppressive activities while the short isoform SYK(S) appears to be associated with tumor promoting activities." (PMID 28957395, 2017). "Although primarily studied in lymphoid cells, numerous solid cancers have been shown to exhibit SYK deregulation, and SYK has been implicated as a putative tumor suppressor gene." (PMID 26243458, 2016). "The activated forms of the BCR-associated kinases LYN and spleen tyrosine kinase (SYK) were present in MCL tumor tissues therefore supporting an in vivo role of active BCR signaling in this pathology." (PMID 23422267, 2013). "Mechanistically, FCGR2A activation in tumor-associated macrophages triggers SYK-dependent PI3K phosphorylation (p-PI3K[Y607]↑2.8-fold vs controls, p=0.004), which subsequently enhances AKT-mediated lipid metabolic reprogramming through SREBP1 activation (mRNA↑3.1-fold, p=0.009)." (PMID 41199823, 2025). "Furthermore, SYK signaling appears to be essential for the polarization of macrophages to the pro‐tumorigenic tumor‐associated macrophage (TAM) phenotype." (PMID 38501219, 2024). "Because of the immunosuppressive microenvironment caused by immunosuppressive cells, the association between SYK expression and pro-tumor immune cells (CD56dim NK cells, immature DCs, MDSCs, neutrophils, plasmacytoid DCs, Tregs, Th2 cells, and M2 macrophages) should be investigated." (PMID 35910221, 2022). "Functionally, SYK might be involved in immune-associated processes and shape the immunosuppressive tumor microenvironment." (PMID 35910221, 2022). "Previous studies also demonstrated a novel Mincle/SYK/NF-κB signaling pathway in which the pattern recognition receptor Mincle was highly expressed in tumor-associated macrophages, thus accelerating M2 polarization and tumor progression." (PMID 35910221, 2022). "Thus, there is a positive correlation between SYK expression and increased risk of tumor metastasis formation." (PMID 34575665, 2021). "It is therefore unclear whether the putative tumour suppressor phenotype associated with SYK deletion is conferred via loss of kinase activity or of the protein itself." (PMID 32292575, 2020). "However, the case for SYK possessing tumour suppressor activity relies on data in which SYK (or SYK-containing allele) is deleted and/or silenced by e." (PMID 32292575, 2020).
tumor (continued). "However, most of these studies have focused on functional outcome in cell lines or associated tumor characteristics to the total mRNA or protein expression of SYK instead of linking mRNA and/or protein expression of SYK to long term clinical outcome." (PMID 28957395, 2017). "However, SYK mRNA or SYK protein expression have been both positively and negatively associated with tumor characteristics such as tumor grade and tumor stage." (PMID 28957395, 2017). "Additionally, the expression of SYK has been implicated in various patterns of CRC by initiating tumor metastasis but could be targeted by curcumin." (PMID 40298630, 2025). "Research has also shown that SYK expression in some solid tumors is associated with increased tumor-infiltrating lymphocytes and better survival; therefore, its decreased expression hints at a potentially affected immune response within the tumor microenvironment and a poorer prognosis." (PMID 39766121, 2024). "A sequence of immune infiltration analyses showed abnormally expressed SYK could contribute to the immunosuppressive tumor microenvironment, caused by immunosuppressive cells (CD56dim NK cells, immature DCs, MDSCs, neutrophils, plasmacytoid DCs, Tregs, Th2 cells, and M2 macrophages)." (PMID 35910221, 2022). "Thus, the Hippo/YAP1 association with SYK needs to be investigated to clarify how it might correlate with its tumor suppressing function." (PMID 33670716, 2021). "Siglec-14 regulates immune cell activity through interactions with SYK, thereby influencing tumor progression." (PMID 40858654, 2025). "Given that tumor cells heavily depend on glucose and glutamine metabolism, it can be reasonably concluded that SYK activation and PDK1 dimerization-mediated AKT activation occur commonly under conditions of both glucose and glutamine deprivation." (PMID 40774947, 2025). "Siglec-5 signaling primarily relies on the recruitment and activation of SHP-1 and SHP-2, which dephosphorylate SYK (phosphorylated by Siglec-14 binding), thereby reducing immune cell anti-tumor activity." (PMID 40858654, 2025). "SIRPα activation recruits SHP-1 and SHP-2, leading to their phosphorylation, which in turn dephosphorylates SYK and suppresses its activation, affecting immune cell anti-tumor functions." (PMID 40858654, 2025). "Subsequent molecular biology experiments corroborated our findings, illustrating heightened SYK expression levels within tumour tissues and its contribution to cancer cell migration." (PMID 38842134, 2024). "We administered pharmacological inhibitors of SYK and specific targeting of mice liver macrophages to investigate the role of SYK in NETosis and the mechanism of its impact on liver injury and tumor recurrence in hepatic ischemia-reperfusion injury." (PMID 39261768, 2024). "The observed upregulation of SYK in tumour tissues, coupled with its correlation with inferior PFS, underscores its clinical significance as a prognostic marker." (PMID 38842134, 2024). "Using flow cytometry and multiphoton imaging they show that inhibition of SYK in vivo attenuates GBM tumor growth and invasiveness and decreases cell mobility and infiltration." (PMID 37107600, 2023). "Activation of these cells produces pro-thrombotic and pro-tumorigenic TF and activates STAT3-mediated IL-6, PAI-1, and MMP-2 production (black upward arrows), and RAS/PI3K/SyK/Ki67/cyclin D1 signaling pathways, leading to tumor growth." (PMID 36751299, 2023). "The previous literature reported that SYK is responsible for immune cell infiltration into the tumor microenvironment." (PMID 35910221, 2022). "The previous literature reported that SYK was responsible for immune cell infiltration into the tumor microenvironment." (PMID 35910221, 2022). "Neutrophils isolated from R788-treated mice showed similar cytotoxicity towards tumor cells as those isolated from control mice, excluding a central role for SYK signaling in the generation of anti-tumor neutrophils." (PMID 35453656, 2022).